SSTR2 (somatostatin receptor 2)
Diseases named in the same sentence as SSTR2 in open-access papers (continued):
Sharing a sentence is not in itself a finding about the gene and the disease.
acromegaly (36 papers, 2013 to 2025). Acromegaly is an acquired disorder related to excessive production of growth hormone (GH) and characterized by progressive somatic disfigurement (mainly involving the face and extremities) and systemic manifestations. "All the eight tumours that caused acromegaly expressed SSTR2 and all but one tumour expressed SSTR5." (PMID 37851558, 2023). "All other tumours causing acromegaly exhibited strong diffuse staining for SSTR2, with weaker but positive staining for SSTR5." (PMID 37851558, 2023). "High SSTR2 expression in this group of tumours causing acromegaly therefore indicates potential therapeutic benefit from SRL if surgery is not an option or does not result in cure." (PMID 37851558, 2023). "A low expression of SSTR2 was described in an acromegaly AIP-mutated patient." (PMID 37958702, 2023). "In the case of acromegaly, SSTR2 is an important receptor due to its expression on adenoma cell membranes." (PMID 39329930, 2024). "Pasireotide has a 30- to 40-fold higher affinity for SSTR5 and lower affinity for SSTR2 compared with octreotide, which is why pasireotide has been attributed with potentially greater clinical efficacy in acromegaly than first-generation SSA." (PMID 38405148, 2024). "If we assume that the effects of the drugs are correlated with the expression of their target receptors, we would expect beneficial results from targeting SSTR3 in NF-PitNETs at least at similar levels as observed when targeting SSTR2 in acromegaly." (PMID 37033229, 2023). "Pasireotide is approved clinically for the treatment of acromegaly displaying binding to multiple SSTR subtypes in order of SSTR5 > SSTR2 > SSTR3 > SSTR1." (PMID 38203605, 2023). "It is known that tumour SSTR2 expression in acromegaly correlates with lowering of serum IGF-1 and GH levels." (PMID 37851558, 2023). "In patients with acromegaly, the SSTR2-specific agonists OCT and lanreotide reduce the GH secretion." (PMID 38203605, 2023). "In the Italian acromegaly population, a low-grade SSTR2 expression seems to be the most relevant predictor of resistance to first-generation somatostatin receptor ligands, followed by a SG/intermediate cytokeratin pattern and a T2-iso/hyperintense MRI signal." (PMID 36614826, 2022). "Our data confirm the presence of reliable predictors of fg-SRL resistance (age at diagnosis, cytokeratin granulation pattern, SSTR2 expression, T2-intensity on MRI, post-operative remnant persistence) in the Italian acromegaly population." (PMID 36614826, 2022). "Pasireotide resistance is possibly more related to SSTR2 expression than to SSTR5 in the general acromegaly population." (PMID 35602875, 2022). "Medical responsiveness results are less heterogeneous than surgical remission among various pathological subtypes, considering a biological rationale about different SSTR2 expressions and medical responsiveness in acromegaly." (PMID 34530798, 2021). "Dopastatin, a novel chimeric analog with dual binding ability to SSTR2 and dopamine receptors (D2), also exhibited an antisecretory effect on GH in acromegaly patients, and antitumor effects in midgut carcinoid cells in vitro." (PMID 33854479, 2021). "Cold SSAs, such as octreotide and lanreotide, have a proclivity to target SSTR2, which have been studied and utilized in various endocrine-related diseases, including GEPNETs and acromegaly." (PMID 33854479, 2021). "It is widely suggested that the response to SRLs treatment in acromegaly correlates with expression of the SSTR2 and SSTR5 subtypes." (PMID 31191457, 2019). "Tumour expression of SSTR2 seems to be the most consistent marker determining the response to SSAs in acromegaly (recently reviewed in 3 and 26)." (PMID 30843342, 2019). "In this study, we demonstrated for the first time in Chinese patients that the expression pattern of SSTR2 was different in the normal pituitary compared to somatotrophic adenomas." (PMID 28396686, 2017).
acromegaly (continued). "SSTR2 agonists have been clinically used for the treatment of acromegaly and pancreatic tumors, whereas ORs are emerging new members of GPCR family for their anti-proliferative role in various tumors." (PMID 24059654, 2013). "Synthetic therapeutic agonists showing selectivity for SSTR2 (Octreotide) or for SSTR2 and SSTR5 (Pasireotide) have been approved for the treatment of patients with acromegaly and Cushing’s syndrome, as their pituitary tumors highly express SSTR2 or SSTR2/SSTR5, respectively." (PMID 37444563, 2023). "The role of SSTR2 and SSTR5 heterodimerizations with enhanced response in acromegaly is further supported with observation describing the weak response of SST ligand in acromegaly with low SSTR2/SSTR5 ratio, as well as in the presence of the Sst5TMD4-truncated isoform of SSTR5." (PMID 38203605, 2023). "Previous studies described greater efficacy of fg-SRL in DG tumors with higher response rate and a greater reduction in IGF-I levels; this observation is, in turn, consistent with the demonstration of a poor SSTR2 representation on cells of somatotroph adenoma with a dot-like cytokeratin pattern." (PMID 36614826, 2022). "A recently published systematic review and consensus treatment guideline takes into account three factors in formulating a personalized approach to medical therapy of acromegaly: granulation pattern, somatostatin receptor 2 (SSTR2) staining and T2 intensity on MRI." (PMID 32843993, 2020). "Additionally, somatostatin receptor type two (SSTR2) expression, which was long-acting somatostatin analogs widely used to treat acromegaly, was nearly two-fold higher in invasive (217.7 ± 19) than those in non-invasive samples (108 ± 27.2, p < 0.01)." (PMID 31508369, 2019). "SSTR2 expression has been also shown to be low in SPAs with immunonegative staining for all pituitary hormones or positive only for glycoprotein hormones (LH/FSH) compared with active somatotroph adenomas." (PMID 30020466, 2019). "Only one cat in the acromegalic group exhibited diffuse strong SSTR2 expression, which suggests that certain individual cats might be suitable candidates to receive octreotide to manage their acromegaly." (PMID 30620005, 2019). "Pre-surgical treatment for acromegaly with somatostatin analogues has been shown to reduce the levels of SSTR2 proteins and could also downregulate the GH gene expression." (PMID 29979686, 2018). "The immunohistochemical detection of SSTR2 might become, in particular, a feasible method to guide the medical treatment of acromegaly patients." (PMID 29266696, 2018). "An inconsistent association between SSTR2 and AIP was clinically suggested from the finding that SSTR2 staining was not always reduced in pituitary somatotroph adenomas regardless of the presence or absence of Aip mutations." (PMID 27706259, 2016). "After much effort has been made over years, an SSTR2 subtype-selective agonist paltusotine has recently been developed by Crinetics, which is an orally bioavailable non-peptide small molecule and is undergoing phase 3 trials for the clinical treatment of acromegaly and other NETs." (PMID 36810324, 2023). "Tumor expression of particular genes was found of prognostic/predictive value in acromegaly patients, These genes include basically CDH1 and SSTR2 but also CDKN1B SNAI2, FLNA, ARRB1, SNAI1 RORC ESRP1, and MKI67." (PMID 39497133, 2024). "The expression of SSTR2 and SSTR5 was recently demonstrated in all the silent somatotroph adenomas reviewed (n = 21); however, expression of SSTR2 was significantly lower compared with the secreting counterpart, and SSTR5 expression was similar in both groups." (PMID 30020466, 2019). "Our aim was to evaluate the value of the immunohistochemical (IHC) scores of 2 subtypes, SSTR2 and SSTR5, in predicting the short-term efficacy of SSA therapy in patients with active acromegaly." (PMID 28396686, 2017).
acromegaly (continued). "Paltusotine is a nonpeptide selective somatostatin receptor 2 agonist in development as once-daily oral treatment for acromegaly." (PMID 38828555, 2024). "From a prognostic point of view, low/absent cytoplasmic SSTR2 expression is correlated with recurrence rate, reintervention probability, and poor response to somatostatin receptor ligands (SRLs) therapy in acromegaly." (PMID 37958702, 2023). "The expression of SSTR2 and ZAC1 was decreased and SSTR3 expression was increased in the hormone-negative tumors and SGAs compared with the active somatotroph adenomas and normal pituitary." (PMID 30020466, 2019). "The clinical relevance of E-Cadherin in the personalized medicine of acromegaly is also highlighted in the ACROFAST trial, which utilized the IHC expression of this marker, without the addition of SSTR2, to stratify patients into standard or personalized treatment arms." (PMID 39201352, 2024).
breast carcinoma (24 papers, 1997 to 2025). "The presence of SSTR2 is considered a favorable factor in breast cancer, associated with low invasion and proliferation." (PMID 32121432, 2020). "In breast cancer cells, treatment with E2 caused up-regulated SSTR2-mRNA expression, while Tam had variable effects depending on the cell line used." (PMID 16018813, 2005). "Needle biopsy specimens at the time of breast cancer diagnosis were positive for somatostatin receptor 2 (SSTR2) and insulin-like growth factor 1 receptor (IGF-1R) immunostaining." (PMID 39238765, 2024). "One study reported that the overexpression of SSTR2 induces apoptosis in breast cancer cells, decreases epidermal growth factor receptor expression, and exhibits antiproliferative effects." (PMID 39238765, 2024). "First, this is the first report of TSH-PitNET combined with breast cancer; second, the breast cancer specimen was positive for SSTR2 and IGF-1R immunoreactivity; third, the breast cancer showed a complete response after treatment with SSA and chemotherapy." (PMID 39238765, 2024). "We report the case of a patient with SSTR2-positive breast cancer and TSH-PitNET who, after treatment with T-DXd and lanreotide, showed marked shrinkage of the breast mass, disappearance of cancer cells, and normalization of pituitary and thyroid functions." (PMID 39238765, 2024). "The overexpression of SSTR2 in MCF-7 breast cancer cells, which are devoid of estrogen receptor α (ERα), induced apoptosis and cell cycle arrest." (PMID 38203605, 2023). "An autoradiographic study on an array of human breast cancer tissues showed that the antagonist [177Lu]DOTABASS had greater binding affinity to SSTR2 in comparison with the established agonist radioligand [177Lu]DOTATATE." (PMID 31652624, 2019). "Chereau and colleagues observed that [68Ga]DOTATOC (DOTA-DPhe1-Tyr3—Octreotide) was able to visualize breast cancer xenografts overexpressing SSTR2 that were undetected using [18F]FDG." (PMID 31652624, 2019). "The gastrin releasing peptide receptor (GRPR) and the somatostatin receptor 2 (SSTR2) are overexpressed on primary breast cancer (BC), making them ideal candidates for receptor-mediated nuclear imaging and therapy." (PMID 28107508, 2017). "Over-expression of SSTR2 in MCF-7 breast cancer cells, which naturally express low levels of SSTR2, led to increased apoptosis and cell cycle arrest." (PMID 25010045, 2014). "In the present study we unfold the effects of activation of SSTR2 and ORs alone or in combination on signaling cascades and cell proliferation in human breast cancer cells including MCF-7, MDA-MB231 and T47D." (PMID 24059654, 2013). "Our observations uncovered the new role of SSTR2 and ORs in combination in regulating the key tumor promoting signals in breast cancer cells." (PMID 24059654, 2013). "In the present study, we determined the changes in SSTR subtype 2 (SSTR2) and μ, δ and κ-ORs expression, signaling cascades and apoptosis in three different breast cancer cells namely MCF-7, MDA-MB231 and T47D." (PMID 24059654, 2013). "In conclusion, this is the first comprehensive study unveiling the molecular mechanisms of SSTR2/ORs mediated anti-proliferative signaling with novel therapeutic implications in breast cancer treatment." (PMID 24059654, 2013). "Taken together, findings indicate a new role for SSTR2/ORs in modulation of signaling pathways involved in cancer progression and provide novel therapeutic approaches in breast cancer treatment." (PMID 24059654, 2013). "Two cancer cell lines, human lung cancer H446 (with high SSTR2 expression) and human breast cancer MCF-7(with low SSTR2 expression), were used in the study." (PMID 24300405, 2013). "Our findings for the first time highlight the molecular mechanisms for the role of SSTR2 and ORs mediated antagonism of tumorigenic signaling pathways in human breast cancer cells in receptor dependent manner." (PMID 24059654, 2013).
breast carcinoma (continued). "Consistent with previous studies, our observations suggest a much pronounced cytotoxic role of SSTR2 and ORs in breast cancer cells." (PMID 24059654, 2013). "Consistent with previous studies in heterologous system, our results showed that SSTR2 exist as pre-formed heterodimers with μ, δ and κ-ORs in breast cancer cells in receptor and cell-specific manner." (PMID 24059654, 2013). "It has been previously shown that SSTR1 and SSTR2 are highly expressed in breast cancer cells and exert an inhibitory role on tumor cell proliferation and migration." (PMID 16018813, 2005). "In summary, our data show that SSTR1 and SSTR2 expression in breast cancer cells is modulated by Tam and E2 in a cell-specific manner." (PMID 16018813, 2005). "SSAs are effective in improving pituitary and thyroid functions against TSH-PiTNET, and in combination with chemotherapy, they may have synergistic antitumor effects in patients with SSTR2-positive breast cancer." (PMID 39238765, 2024). "The combination of SSAs and chemotherapy for patients with breast cancer with positive SSTR2 expression may be a new treatment to achieve synergistic antitumor effects." (PMID 39238765, 2024). "Moreover, early studies have shown that SSTR2 is the most widely expressed SSTR subtype in breast cancer." (PMID 33318294, 2020). "Most breast cancers (50–70%) overexpress SSTR (mostly SSTR2) compared to normal tissues." (PMID 32121432, 2020). "However, in breast cancers that express truncated variant SSTR5-TMD4, the beneficial function of SSTR2 is compromised." (PMID 32121432, 2020). "However, in line with previous studies from our and other groups, the SSTR antagonist JR11 clearly shows superiority to the SSTR agonist octreotate for targeting breast cancer, also in the endogenously SSTR2 expressing breast cancer cell line ZR75–1." (PMID 29503852, 2017). "However, SSTR2 and OR subtypes mediated effect on signaling pathways in part are dependent on the presence of ER in breast cancer cells is still elusive." (PMID 24059654, 2013). "Whether SSTR2 functionally interacts with ORs in breast cancer cells expressing these receptors endogenously and function in similar manner as described in heterologous system is largely elusive." (PMID 24059654, 2013). "In the present study, we focus to determine the expression of SSTR2 and ORs and the changes in receptor expression and signaling pathways upon treatment with receptor specific agonist in human breast cancer cell lines; MCF-7 (ER + ve), MDA-MB231 (ER-ve), and T47D (ER + ve)." (PMID 24059654, 2013). "We hypothesize that the simultaneous activation of SSTR2 and ORs may exert pronounced anti-proliferative effect via changes in signaling pathways in breast cancer cells." (PMID 24059654, 2013). "Therefore, targeting SSTR2 and specific ORs could possibly be a better therapeutic approach in breast cancer treatment." (PMID 24059654, 2013). "Although this is unlikely to have diagnostic or prognostic significance, SSTR2-specific somatostatin analogues may have therapeutic potential in breast cancer." (PMID 9062398, 1997). "Recently, SSTR2 and IGF-1R were reported to be expressed in breast cancer, and several clinical trials of SSAs for breast cancer have been conducted." (PMID 39238765, 2024). "The increased tumor binding with antagonists opens up the potential indications for SSTR2 targeting to tumors which have a relatively lower expression of SSTR2 compared to NET such as small cell lung cancer, hepatocellular carcinoma and breast cancer." (PMID 36387893, 2022). "Given the receptor dependent role, SSTR2 and ORs regulating the MAPK and PI3K/AKT pathways in breast cancer cells is an indication of inhibition of EGFR functions." (PMID 24059654, 2013).
breast carcinoma (continued). "Multiple studies have documented that estrogen upregulated the expression of SSTR2 mRNA and protein via ER in T47D and ZR75-1 (ER + ve) breast cancer cells." (PMID 24059654, 2013). "Oct conferred high selectivitytoward SSTR2-overexpresing HER2+ breast cancer cells, evenin heterogeneous environments containing nontumor cells." (PMID 41283704, 2025). "In fact, the expression of SSTR2 has been reported in approximately 50-90% of breast cancers but has not been confirmed in normal breast tissue." (PMID 39238765, 2024). "Recently, somatostatin receptor 2 (SSTR2) and insulin-like growth factor 1 receptor (IGF-1R) have been reported to be expressed in breast cancer, and several clinical trials of SSAs in breast cancer have been conducted." (PMID 39238765, 2024). "Furthermore, SSTR2 and SSTR3 regulate intracellular signaling and apoptosis in receptor and cell-specific manner in breast cancer cells." (PMID 38203605, 2023). "Antagonists have a higher tumor binding to receptors than agonists, opening up the potential indications for SSTR2 targeting to tumors which have a relatively lower expression of SSTR2 compared to NET such as small cell lung cancer, hepatocellular carcinoma and breast cancer." (PMID 36387893, 2022). "Sstr2 expression strongly correlates with luminal A markers (estrogen and progesterone receptor), and is typically not found in the other breast cancer subtypes." (PMID 29503845, 2017). "Interestingly, p38 mediated anti-apoptotic effects typically seen in breast cancer are remarkably diminished in MDA-MB231 and T47D cells upon activation of SSTR2 and ORs." (PMID 24059654, 2013).